SLC44A3 (solute carrier family 44 member 3)
Synonyms: CTL3; MGC45474
Tractability: Antibody: its Gene Ontology location is reachable by antibodies, with high confidence; UniProt predicts a signal peptide or a membrane-spanning region. PROTAC: ubiquitination databases record sites on it.
Gene: Protein-coding gene on chromosome 1 (94,820,278 to 94,895,246, forward strand). Ensembl gene ENSG00000143036.
Subcellular location: Membrane
Pathways (Reactome):
Metabolism: Synthesis of PC
Transport of small molecules: SLC-mediated bile acid transport
Gene Ontology:
Molecular function: protein binding; choline transmembrane transporter activity; transmembrane transporter activity
Biological process: bile acid and bile salt transport; phosphatidylcholine biosynthetic process; transmembrane transport; choline transport
Cellular component: plasma membrane; membrane
Genetic constraint (gnomAD): Loss-of-function variants: 69 observed, 71.7 expected, observed/expected ratio (o/e) 0.96, 90% interval 0.79 to 1.18. The upper end of that interval is the gene's LOEUF score, 1.18, which puts it in group 5 of 6, group 1 being the genes least tolerant of losing a copy. Missense variants: 654 observed, 755.63 expected, observed/expected ratio (o/e) 0.87, 90% interval 0.81 to 0.92. Synonymous variants: 289 observed, 288.82 expected, observed/expected ratio (o/e) 1, 90% interval 0.91 to 1.1.
Homologues: Orthologues: chimpanzee SLC44A3 (99% identical), macaque SLC44A3 (89% identical), rabbit SLC44A3 (83% identical), guinea pig SLC44A3 (83% identical), dog SLC44A3 (83% identical), pig SLC44A3 (83% identical), rat Slc44a3 (81% identical), mouse Slc44a3 (81% identical), tropical clawed frog SLC44A3 (58% identical), zebrafish slc44a1a (45% identical), Drosophila melanogaster Ctl1 (33% identical), Drosophila melanogaster Ctl2 (24% identical), and 1 more. Paralogues in human: SLC44A1 (47% identical), SLC44A2 (28% identical), SLC44A5 (27% identical), SLC44A4 (26% identical).
Diseases named in the same sentence as SLC44A3 in open-access papers:
SLC44A3 is named in the same sentence as 5 diseases in open-access papers, as found by Europe PMC text mining. Sharing a sentence is not in itself a finding about the gene and the disease. The quoted sentences say what the papers report.
tumor (5 papers, 2020 to 2023). "We also constructed a prognostic risk model using the four LMRGs signatures, including ENPP2, MGLL, PLCD1, and SLC44A3, and we found that most of them were correlated with tumor progression." (PMID 37033945, 2023). "Interestingly, the results observed that 5 hub genes were shared in the GEO and TCGA profiles, including SLC44A3, DBF4, NAPSA, ATP6V0A4, and CLDN4, which were closely associated with B cells, CD4+ T cells, CD8+ T cells, Macrophage, Neutrophil, and Dendritic cells to involve in tumor immunity." (PMID 36325324, 2022).
neurodegenerative disease (1 paper, 2024). A disorder of the central nervous system characterized by gradual and progressive loss of neural tissue and neurologic function. "A choline deficiency caused by mutations in the SCL44A1 gene, a close homolog of SLC44A3, is known to cause neurodegenerative disease, with abnormal regulation of the genes involved in mitochondrial fatty acid transport and β-oxidation, and evidence of disturbances in fatty acid homeostasis." (PMID 38674343, 2024).
SLC44A3 also shares sentences with these, for which no sentence is quoted: cancer (2 papers); glioma (1); infection (1).